MAPK8IP1P2 (mitogen-activated protein kinase 8 interacting protein 1 pseudogene 2)
Gene: Processed pseudogene on chromosome 17 (45,600,869 to 45,602,340, reverse strand). Ensembl gene ENSG00000263503.
Diseases named in the same sentence as MAPK8IP1P2 in open-access papers:
MAPK8IP1P2 is named in the same sentence as 5 diseases in open-access papers, as found by Europe PMC text mining. Sharing a sentence is not in itself a finding about the gene and the disease. The quoted sentences say what the papers report.
thyroid cancer (2 papers, 2020 to 2023). "Gain and loss of function assays demonstrated that upregulating MAPK8IP1P2 inhibited, while silencing MAPK8IP1P2 promoted anoikis resistance in vitro and lymphatic metastasis of thyroid cancer cells in vivo." (PMID 33489905, 2020). "Therefore, our results provide novel insights into the underlying mechanism by which MAPK8IP1P2 inhibits lymphatic metastasis in thyroid cancer, supporting the notion that MAPK8IP1P2 can be used as a lymph node metastatic marker in thyroid cancer." (PMID 33489905, 2020). "Therefore, our results combined with TCGA analysis suggest that downexpression of MAPK8IP1P2 may be implicated in lymphatic metastasis of thyroid cancer." (PMID 33489905, 2020). "By analyzing RNA sequencing dataset of thyroid cancer from The Cancer Genome Atlas (TCGA), we found that MAPK8IP1P2 was marked downregulated in thyroid cancer tissues compared with that in the adjacent normal tissues (ANT)." (PMID 33489905, 2020). "Consistently, MAPK8IP1P2 expression was reduced in our 24 paired thyroid cancer tissues compared with the matched ANT." (PMID 33489905, 2020). "Collectively, our results demonstrate that MAPK8IP1P2 inhibits anoikis resistance by sponging miR-146b-3p in thyroid cancer cells." (PMID 33489905, 2020). "Mitochondrial potential assay showed that upregulating MAPK8IP1P2 attenuated, while silencing MAPK8IP1P2 elevated the mitochondrial potential of thyroid cancer cells." (PMID 33489905, 2020). "The critical findings of the current study present novel insights into the pivotal role of MAPK8IP1P2 in lymphatic metastasis of thyroid cancer by the miR-146b-3p/Hippo signaling axis." (PMID 33489905, 2020). "MAPK8IP1P2-mediated this lncRNA/mRNA crosstalk activated Hippo signaling, which further inhibited anoikis resistance and lymphatic metastasis in thyroid cancer." (PMID 33489905, 2020). "MAPK8IP1P2 was differentially downregulated in thyroid cancer cells compared with that in PTFE cells." (PMID 33489905, 2020). "In contrast, our results further revealed that miR-146b-3p mimics attenuated the stimulatory effects of MAPK8IP1P2 overexpression on the apoptotic ratio and activity of caspase-3 or -9 in thyroid cancer cells." (PMID 33489905, 2020). "Then, the effect of MAPK8IP1P2 on lymphatic metastasis of thyroid cancer cells in vivo was further investigated using the inguinal lymph node metastasis model." (PMID 33489905, 2020). "Here, we reported that MAPK8IP1P2 was downregulated in thyroid cancer tissues with lymphatic metastasis." (PMID 33489905, 2020). "Upregulating MAPK8IP1P2 enhanced, while silencing MAPK8IP1P2 reduced the apoptosis rate of thyroid cancer cells." (PMID 33489905, 2020). "Upregulating MAPK8IP1P2 inhibited, while silencing MAPK8IP1P2 enhanced anoikis resistance in vitro and lymphatic metastasis of thyroid cancer cells in vivo." (PMID 33489905, 2020). "Taken together, our results indicate that upregulating MAPK8IP1P2 abrogates anoikis resistance in thyroid cancer cells." (PMID 33489905, 2020). "Here, we reported that MAPK8IP1P2 was dramatically downregulated in thyroid cancer tissues, especially in those with lymph node metastasis." (PMID 33489905, 2020). "First, the expression levels of MAPK8IP1P2 in 7 thyroid cancer cell lines and a normal thyroid follicular epithelial cell line PTFE were measured." (PMID 33489905, 2020). "Gain and loss of function assays showed that upregulating MAPK8IP1P2 inhibited, while silencing MAPK8IP1P2 enhanced anoikis resistance in vitro and lymphatic metastasis of thyroid cancer cells in vivo." (PMID 33489905, 2020). "In the current study, we found that MAPK8IP1P2 was downregulated in thyroid cancer tissues, and particularly in thyroid cancer tissues with lymphatic metastasis, which was correlated with poor progression-free survival in thyroid cancer patients." (PMID 33489905, 2020).
thyroid cancer (continued). "The only miR-146b-3p expression level was negatively correlated with MAPK8IP1P2 expression, and was upregulated in thyroid cancer tissues compared with that in ANT." (PMID 33489905, 2020). "TCGA analysis further supported this finding that MAPK8IP1P2 expression was reduced in thyroid cancer tissues compared with that in ANT, especially in thyroid cancer tissues with lymph node metastasis." (PMID 33489905, 2020). "Thus MAPK8IP1P2 acts as an oncosuppressor lncRNA with anti-lymphangiogenic properties, inhibiting lymphatic metastasis in thyroid cancer via the activation of Hippo signaling." (PMID 37407839, 2023). "Notably, upregulating MAPK8IP1P2 represses anchorage-independent growth capability of thyroid cancer cells." (PMID 33489905, 2020). "Therefore, we further explored the potential binding miRNAs of MAPK8IP1P2 by analyzing the correlation of MAPK8IP1P2 with all reported miRNAs in the thyroid cancer dataset from TCGA." (PMID 33489905, 2020). "Therefore, our results unravel a novel mechanism by which MAPK8IP1P2 inhibits the anoikis resistance and lymphatic metastasis of thyroid cancer cells, determining the tumor-suppressive role of MAPK8IP1P2 in lymphatic metastasis of thyroid cancer." (PMID 33489905, 2020). "Importantly, miR-146b-3p mimics reversed the inhibitory effect of MAPK8IP1P2 overexpression on anoikis resistance of thyroid cancer cells." (PMID 33489905, 2020). "In conclusion, our findings suggest that MAPK8IP1P2 may serve as a potential biomarker to predict lymphatic metastasis in thyroid cancer, or a potential therapeutic target in lymphatic metastatic thyroid cancer." (PMID 33489905, 2020). "Therefore, the effect of MAPK8IP1P2 on anoikis resistance in thyroid cancer cells was further evaluated." (PMID 33489905, 2020). "Similarly, neither colony-formation ability nor cell cycle progression was impeded by the changed expression of MAPK8IP1P2 in thyroid cancer cells." (PMID 33489905, 2020). "We further investigated whether miR-146b-3p mediates the effect of MAPK8IP1P2 on anoikis resistance in thyroid cancer cells." (PMID 33489905, 2020). "However, upregulating MAPK8IP1P2 inhibited, while silencing MAPK8IP1P2 increased anchorage-independent growth capability of thyroid cancer cells." (PMID 33489905, 2020). "Therefore, our findings uncover a novel mechanism by which MAPK8IP1P2 inhibits the anoikis resistance and lymphatic metastasis of thyroid cancer cells." (PMID 33489905, 2020). "The basic information of 48 thyroid carcinoma patients for MAPK8IP1P2 RNA expression analysis." (PMID 33489905, 2020). "Importantly, miR-146b-3p mimics not only reversed the NF2, RASSF1, and RASSF5 level enhanced by MAPK8IP1P2 overexpression, but also inactivated Hippo signaling in MAPK8IP1P2-overexpressing thyroid cancer cells as indicated by elevated the luciferase reporter activity of HOP-Flash." (PMID 33489905, 2020). "Taken together, our findings provide the experimental evidence regarding the clinical significance and biological role of MAPK8IP1P2 in lymphatic metastasis of thyroid cancer, suggesting that MAPK8IP1P2 may be used as a potential biomarker to predict lymphatic metastasis in thyroid cancer patients." (PMID 33489905, 2020). "Collectively, our findings clarify that MAPK8IP1P2 activates Hippo signaling by sponging miR-146b-3p to disrupt the inhibitory effect of miR-146b-3p on NF2, RASSF1, and RASSF5 expression in thyroid cancer." (PMID 33489905, 2020). "We further constructed MAPK8IP1P2-stably overexpressing B-CPAP and K1 cells and endogenously knocked down MAPK8IP1P2 expression in B-CPAP and K1 cells, both of which expressed moderate levels of MAPK8IP1P2 compared with that in other thyroid cancer cell lines." (PMID 33489905, 2020).
thyroid cancer (continued). "In the current study, our results showed that MAPK8IP1P2 activated Hippo signaling by sponging miR-146b-3p to disrupt targeting effect of miR-146b-3p on NF2, RASSF1, and RASSF5, which inhibited anoikis resistance and lymphatic metastasis of thyroid cancer." (PMID 33489905, 2020). "Mechanistically, MAPK8IP1P2 activated Hippo signaling by sponging miR-146b-3p to disrupt the inhibitory effect of miR-146b-3p on NF2, RASSF1, and RASSF5 expression, which further inhibited anoikis resistance and lymphatic metastasis in thyroid cancer." (PMID 33489905, 2020). "Luciferase reporter assay showed that upregulating MAPK8IP1P2 reduced, while silencing MAPK8IP1P2 increased the luciferase reporter activity of HOP-Flash, but not the HIP-Flash, suggesting that upregulating MAPK8IP1P2 inhibits the TEAD-dependent luciferase activity in thyroid cancer cells." (PMID 33489905, 2020). "Mechanistic investigations revealed that MAPK8IP1P2 activated Hippo signaling by sponging miR-146b-3p to disrupt the inhibitory effect of miR-146b-3p on NF2, RASSF1, and RASSF5 expression, which further inhibited anoikis resistance and lymphatic metastasis in thyroid cancer." (PMID 33489905, 2020). "In summary, our results demonstrate that MAPK8IP1P2 activates Hippo signaling by sponging miR-146b-3p as a ceRNA to disrupt the inhibitory effect of miR-146b-3p on NF2, RASSF1, and RASSF5 expression, which further suppresses lymphatic metastasis of thyroid cancer." (PMID 33489905, 2020). "Interestingly, we found that downexpression of MAPK8IP1P2 occurred in 4/9 (44.4%) thyroid cancer tissues without lymph node metastasis, and was 10/15 (66.7%) in thyroid cancer tissues with lymph node metastasis." (PMID 33489905, 2020).
cancer (1 paper, 2020). A tumor composed of atypical neoplastic, often pleomorphic cells that invade other tissues. "Our results further revealed that upregulating MAPK8IP1P2 activated Hippo signaling by disrupting the repressive effect of miR-146b-3p on NF2, RASSF1, and RASSF5 expression by sponging miR-146b-3p as ceRNA, which further suppressed anoikis resistance in thryoid cancer cells." (PMID 33489905, 2020).
tumor (1 paper, 2020). "Conversely, the tumors in lymph nodes formed from MAPK8IP1P2-downexpressing cells had larger tumor burden and more number of tumor cells than those inoculated with the scramble cells." (PMID 33489905, 2020).
MAPK8IP1P2 also shares sentences with these, for which no sentence is quoted: lymph node metastasis (1 paper); Lymphatic Metastasis (1).